HDGF (heparin binding growth factor)
Diseases named in the same sentence as HDGF in open-access papers (continued):
Sharing a sentence is not in itself a finding about the gene and the disease.
breast carcinoma (19 papers, 2002 to 2026). "Herein, we found that high HDGF levels are expressed significantly in breast cancer and exhibit a positive association with poor survival prognosis." (PMID 34376200, 2021). "Our in vivo experiments demonstrated that HDGF downregulation inhibited breast cancer radioresistance, suggesting its potential association with breast cancer radioresistance." (PMID 34376200, 2021). "The Hepatoma-derived growth factor (HDGF) is now recognized as a breast cancer-associated gene and promotes the epithelial-mesenchymal transition (EMT)." (PMID 29108258, 2017). "Also, we uncovered the role of HDGF in radioresistant breast cancer both in vitro and in vivo and explored its underlying molecular mechanism." (PMID 34376200, 2021). "Therefore, to establish the association of HDGF with radioresistance of breast cancer, we prepared the clonogenic assay to assess the survival fraction." (PMID 34376200, 2021). "High nuclear expression of HDGF, another gene constituting our 3-gene signature, was earlier found to associate with high tumor grade, Ki-67 >20 %, lymph node involvement and poor prognosis in breast cancer patients." (PMID 25559688, 2015). "Pleiotrophin (PTN), a heparin-binding growth factor with potent mitogenic and angiogenic activity, has emerged as a key regulator of mammary gland biology and a potential driver of breast cancer progression." (PMID 42193935, 2026). "Studies have indicated that HDGF promotes chemotherapy resistance in colorectal cancer cells and tongue squamous cell carcinoma, and it drives radioresistance in breast cancer." (PMID 37301856, 2023). "Studies have indicated that HDGF expression is regarded as a prognostic factor in patients with early-stage NSCLC; HDGF also promotes chemotherapy resistance in some tumors, including colorectal cancer, tongue squamous cell cancer, and breast cancer." (PMID 37301856, 2023). "Our data demonstrated that NAP1L1 functions as a potential oncogene via interacting with HDGF to recruit c-Jun in breast cancer." (PMID 34774047, 2021). "In the present study, we found dramatically upregulated HDGF levels in radioresistant breast cancer cells." (PMID 34376200, 2021). "This article demonstrates the novel function of HDGF as a promising molecular target for predicting radioresistance in breast cancer." (PMID 34376200, 2021). "The confocal microscopic images showed the colocalization of NAP1L1 and HDGF in the cytoplasm of breast cancer cells." (PMID 34774047, 2021). "The combined Stattic treatment with HDGF depletion was more effective on the radiation cell proliferation and cell survival fraction compared to single-agent treatment in both breast cancer cell lines." (PMID 34376200, 2021). "Compared to the control cells, the mRNA and protein levels of HDGF were markedly higher in radioresistant breast cancer cells." (PMID 34376200, 2021). "We validated the actual role of HDGF in the radioresistance of breast cancer, shRNA-mediated HDGF knockdown." (PMID 34376200, 2021). "Meanwhile, HDGF protein expression in breast cancer (MCF7, BT549, MDA-MB-231, and MDA-MB-453) was higher compared to that in the normal MCF10A cells." (PMID 34376200, 2021). "For this experiment, we purified the HDGF complex using Flag pull-down from MDA-MB-231 cells overexpressing Flag-tagged HDGF or a Flag-GFP control to reveal the HDGF regulatory mechanism of radioresistance in breast cancer." (PMID 34376200, 2021). "This EMT process was partly verified in breast cancer cells with counterevidence, in which HDGF overexpression stimulates the cell invasion and metastasis by decreasing E-cadherin expression and increasing Vimentin expression." (PMID 29300772, 2018). "HDGF is overexpressed in several types of cancers including breast cancer cell lines and tissues and correlates with poor prognosis." (PMID 29108258, 2017). "S100A10 has been reported as the 3′-partner gene in the HDGF/S100A10 fusion gene which was found in the UACC-812 breast cancer cell line." (PMID 24604026, 2014).
breast carcinoma (continued). "Pleiotrophin is a heparin-binding growth factor involved in the differentiation and proliferation of neuronal tissue during embryogenesis, and also secreted by melanoma and breast carcinoma cells." (PMID 11953815, 2002). "As reported, HDGF participated in the development of chemotherapy drug resistance in colorectal cancer and tongue squamous cell carcinoma or promoted radioresistance in breast cancer." (PMID 37301856, 2023). "Here, NAP1L1 was found to combine with HDGF by Co-IP examination in breast cancer cells." (PMID 34774047, 2021). "The potential association of HDGF with TKT and STAT3 promotes STAT3-Y705 phosphorylation and inhibits STAT3-S727 phosphorylation enhancing STAT3 transcriptional activity, thereby increasing tumor radioresistance in breast cancer." (PMID 34376200, 2021). "Considering the critical role of the STAT3 signaling pathway in HDGF/TKT-driven breast cancer radioresistance, we assessed the effects of Stattic treatment combined with HDGF-depletion on breast cancer radioresistance using the MDA-MB-231 cells xenograft models." (PMID 34376200, 2021). "We found positive HDGF amplification in breast cancer tumors." (PMID 34376200, 2021). "Additionally, the binding of RXRα to HDGF promoter blocked HDGF transcriptional activity, consequently inhibiting breast cancer radioresistance." (PMID 34376200, 2021). "Here, we tried to use CoIP to confirm the interaction of HDGF with NAP1L1 in breast cancer." (PMID 34774047, 2021). "The Co-IP assay shows the interaction between c-Jun and HDGF in breast cancer." (PMID 34774047, 2021). "HDGF has been widely documented as an oncogene, inducing tumor occurrence and development including endometrial cancer, nasopharyngeal carcinoma, non-small cell lung cancer, liver cancer, and breast cancer." (PMID 34368121, 2021). "Nevertheless, the precise role of HDGF in the radioresistance of breast cancer remains largely unknown." (PMID 34376200, 2021). "Furthermore, RXRα agonist, 9cRA, rescued HDGF overexpression-increased the survival fraction and cell proliferation after I.R. Taken together, the present findings demonstrate that HDGF is critical in RXRα suppression of breast cancer radioresistance." (PMID 34376200, 2021). "Heparin-binding growth factor (HDGF) was upregulated in radioresistant breast cancer cells, however, its knockdown could reduce breast cancer radioresistant both in vitro and in vivo." (PMID 34376200, 2021). "Eventually, we found HDGF expression in radioresistant and control breast cancer cells." (PMID 34376200, 2021). "Thus, its overexpression in breast cancer tissues is in concordance with our results demonstrating the overexpression of HDGF in LCLs of BRCAX individuals affected with breast cancer." (PMID 29108258, 2017). "Moreover, HDGF protein also regulates the EMT in breast cancer cells through modulation of E-cadherin and vimentin expression." (PMID 23536873, 2013). "Thus, HDGF depletion combined with STAT3 activity inhibition impedes breast cancer radioresistance." (PMID 34376200, 2021). "Our results reveal the critical roles of the HDGF-TKT-STAT3 signaling pathway in breast cancer radioresistance; thus, it is a promising therapeutic molecular target for breast cancer." (PMID 34376200, 2021). "It functions as a potential oncogene that interacts with HDGF to recruit c-Jun and thus stimulates CCND1 expression to induce cell cycle transition, finally promoting cell proliferation in breast cancer." (PMID 34774047, 2021). "A bioinformatics analysis was conducted to determine the differential expression of NAP1L1 in breast cancer and find the potential biomarker that interacts with NAP1L1 and hepatoma-derived growth factor (HDGF)." (PMID 34774047, 2021). "Blockade of HDGF using a specific antibody results in the inhibition of malignant features and EMT of breast cancer cells." (PMID 29108258, 2017).
breast carcinoma (continued). "Our recent study demonstrated that HDGF up-regulation is correlated with recurrence, lymph node metastasis and EMT in breast cancer patients." (PMID 23536873, 2013). "Furthermore, NAP1L1 was observed to be an interaction factor of HDGF, recruiting the key oncogenic transcription factor c-Jun and thus inducing the expression of cell cycle promoter CCND1, which finally stimulated breast cancer proliferation." (PMID 34774047, 2021). "Transcript levels of five of the seven metabolic genes (TALDO1, GPI, SHMT2, LDHA, and ADK: 5-gene metabolic signature) and six oncogenes: TAGLN2, NOLC1, HSP90AB1, HDGF, MCM5, and NCL, were elevated in TNBC patients when compared to patients with ER+ breast cancer." (PMID 34711841, 2021). "NAP1L1 interacted with the HDGF, an oncogenic factor for tumors, and the latter subsequently recruited the key oncogenic transcription factor c-Jun, which finally induced the expression of cell cycle promoter Cyclin D1(CCND1) and thus the cell growth of breast cancer." (PMID 34774047, 2021). "However, there are no reports on the explicit role of HDGF in the radioresistance of breast carcinoma." (PMID 34376200, 2021). "Moreover, HDGF, a secreted growth factor, is correlated with EMT process in breast cancer cells." (PMID 29300772, 2018).
non-small cell lung carcinoma (17 papers, 2009 to 2025). A group of at least three distinct histological types of lung cancer, including non-small cell squamous cell carcinoma, adenocarcinoma, and large cell carcinoma. "Besides, HDGF was noted to be an independent risk factor for the prognosis of various malignancies such as liver, gastric, cholangiocarcinoma, and non-small cell lung cancers." (PMID 33292199, 2020). "Use of HDGF antibody therapy has significantly increased the antineoplastic activity of gemcitabine, bevacizumab, and chemotherapy in non-small cell lung cancer." (PMID 34368121, 2021). "High HDGF levels in serum of non-small cell lung cancer patients also indicated bone metastasis and unfavorable prognosis." (PMID 34021184, 2021). "Clinical studies reveal that high HDGF levels also occur in non-small cell lung cancer, colorectal cancer, pancreatic cancer and melanoma." (PMID 30513684, 2018). "Recent reports have shown that high nuclear expression of HDGF facilitates the progression and poor prognosis in some primary cancers, including hepatocellular, gastric, pancreatic, non-small-cell lung cancers, and gastrointestinal stromal tumors." (PMID 24692842, 2014). "Down-regulation of miR-497 may contribute to tumor growth and angiogenesis by targeting HDGF (hepatoma-derived growth factor) in non-small cell lung cancer." (PMID 26486082, 2015). "During cancer development, high levels of HDGF were detected in various human cancers, and its level has been demonstrated as a prognostic factor for several cancers including gastric, HCC, non-small-cell lung cancer, esophageal carcinoma and pancreatic cancer." (PMID 20846397, 2010).
glioma (16 papers, 2014 to 2025). A benign or malignant brain and spinal cord tumor that arises from glial cells (astrocytes, oligodendrocytes, ependymal cells). "High HDGF expressions in gliomas were significantly associated with WHO grades II~IV, KPS <80, Ki-67 index ≥20%, and recurrence." (PMID 34959221, 2021). "Moreover, rescue experiments implicated that restoration of HDGF abrogated SNHG3 silencing induced suppressive effect on glioma cell proliferation." (PMID 33817254, 2020). "HDGF knockdown in glioma cells, which originate from NPCs and/or OPCs, inhibits their proliferation via inhibition of PI3K/Akt signalling pathway." (PMID 35293825, 2022). "The high expressions of NAP1L1 or/and HDGF in glioma tissues indicate shorter overall survival in glioma patients." (PMID 34959221, 2021). "Immunofluorescence analyses illustrated that c-Jun and HDGF proteins mostly co-localized in the cytoplasm of glioma cells; minor nuclear distribution was also observed." (PMID 34959221, 2021). "Consistent with the mRNA levels, expression of the HDGF protein was dramatically upregulated in glioma." (PMID 34959221, 2021). "Our previous study indicated that patients with glioma had a poor prognosis when expression of HDGF was abnormal." (PMID 34959221, 2021). "Next, western blotting was performed to evaluate the reversal upon c-Jun-overexpression on glioma cell proliferation due to HDGF knockdown." (PMID 34959221, 2021). "In this study, we verified that the mRNA levels of HDGF were increased in 24 gliomas as compared to the corresponding 24 para-tumor tissue samples." (PMID 34959221, 2021). "Immunohistochemistry indicated that NAP1L1 and hepatoma-derived growth factor (HDGF) were enhanced in glioma as compared to the para-tumor tissues." (PMID 34959221, 2021). "Immunohistochemical (IHC) staining for the expressions of NAP1L1 and HDGF showed that NAP1L1 positive signals were mostly localized to the cytoplasm of glioma cells, while those of HDGF was mainly in the cytoplasm and nuclei." (PMID 34959221, 2021). "To determine the role of NAP1L1 and HDGF in glioma, we analysed the protein level expressions of NAP1L1 and HDGF by immunostaining in 108 glioma tissues and 24 para-tumor tissues." (PMID 34959221, 2021). "Correlation analysis indicated a significantly positive correlation between NAP1L1 and HDGF expressions in glioma tissues (r = 0.279, P = 0.003)." (PMID 34959221, 2021). "The correlation of NAP1L1 or HDGF protein expression with clinicopathological parameters in gliomas." (PMID 34959221, 2021). "We discovered that SNHG3 acts as an oncogene in glioma to promote cell progression by upregulating HDGF expression through interaction with miR-384." (PMID 33817254, 2020). "LncRNA SNHG3 promotes cell proliferation, migration, and invasion in glioma by enhancing HDGF expression via miR-384 sponging, representing the promising targets for the development of novel therapeutic strategies." (PMID 33817254, 2020). "The expression of SNHG3 and HDGF was upregulated, whereas miR-384 was downregulated in glioma tissues, compared with the normal tissues." (PMID 33817254, 2020). "The regulatory network of SNHG3/miR-384/HDGF axis in glioma progression was validated by qRT-PCR and western blot assay." (PMID 33817254, 2020). "In conclusion, we clarified the regulatory effect of SNHG3/miR-384/HDGF axis on glioma cell proliferation, migration, invasion, and apoptosis." (PMID 33817254, 2020). "Meanwhile, restoration of HDGF abrogated the inhibition of SNHG3 silencing on glioma cell progression." (PMID 33817254, 2020). "Moreover, knockdown of endogenous HDGF enhances glioma cell sensitivity to temolozolomide, a brain tumour chemotherapy drug." (PMID 35293825, 2022). "In a disease state, endogenous HDGF regulates glioma cell proliferation, migration and invasion." (PMID 35293825, 2022). "HDGF is considered a potential therapeutic target for gliomas." (PMID 35874843, 2022).
glioma (continued). "Hepatoma-derived growth factor (HDGF) is a growth factor that promotes angiogenesis and is upregulated in gliomas, HDGF eventually forms a complex with β-catenin from the Wnt pathway; this upregulation of Wnt and HDGF develops tumor generation, progression, and metastasis." (PMID 35328780, 2022). "Taken together, these results demonstrated that c-Jun enhanced upon HDGF overexpression could promote glioma cell proliferation by inducing the activation of the CCND1/CDK4/CDK6 signaling axis." (PMID 34959221, 2021). "The findings demonstrated that NAP1L1 interacted with HDGF in glioma." (PMID 34959221, 2021). "Correlation between NAP1L1 and HDGF expression in glioma tissues." (PMID 34959221, 2021). "Nonetheless, the specific details of HDGF-induced proliferation of glioma remain unexplored." (PMID 34959221, 2021). "Next, the prognostic implications of NAP1L1 and HDGF in gliomas were assessed." (PMID 34959221, 2021). "Similarly, high expression of HDGF was positively correlated with WHO grade, KPS, Ki-67 index, and recurrence, which suggested that HDGF was also involved in glioma progression." (PMID 34959221, 2021). "In summary, NAP1L1 could promote proliferation and chemoresistance in glioma cells by interacting with HDGF and activating c-Jun to induce the expressions of CCND1/CDK4/CDK6." (PMID 34959221, 2021). "Taken together, these results demonstrated that HDGF-mediated c-Jun regulation could promote glioma cell proliferation by inducing CCND1/CDK4/CDK6." (PMID 34959221, 2021). "HDGF knockdown in NAP1L1-overexpressing glioma cells significantly inhibited cell proliferation." (PMID 34959221, 2021). "Moreover, NAP1L1 expression was also positively correlated with the HDGF expression in glioma tissues." (PMID 34959221, 2021). "Moreover, NAP1L1 expression was positively correlated with the expression of HDGF in glioma tissues." (PMID 34959221, 2021). "Moreover, SNHG3 or HDGF knockdown significantly suppressed proliferation, migration, and invasion and induced apoptosis in glioma." (PMID 33817254, 2020). "Moreover, HDGF mRNA levels were repressed by miR-384 mimics and boosted by miR-384 inhibitor in glioma." (PMID 33817254, 2020). "Therefore, we concluded that HDGF functions as an oncogene to accelerate cell growth as well as to suppress apoptosis in glioma." (PMID 33817254, 2020). "Hepatoma-derived growth factor (HDGF) is an angiogenesis-promoting growth factor that is upregulated in gliomas, which ultimately forms a complex with β-catenin from the Wnt pathway; this upregulation from Wnt and HDGF can promote tumor generation, progression and metastasis." (PMID 33322413, 2020). "Altogether, SNHG3 promotes glioma cell development by regulating HDGF." (PMID 33817254, 2020). "In addition, SNHG3 or HDGF knockdown significantly attenuated glioma cell progression; however, restoration of HDGF expression remarkably enhanced proliferation, migration, and invasion in glioma." (PMID 33817254, 2020). "Likewise, the number of migration and invasion cells was reduced in glioma cells after HDGF silencing." (PMID 33817254, 2020). "AGAP2-AS1 could facilitate glioma growth by up-regulating hepatoma-derived growth factor (HDGF)." (PMID 36353102, 2022). "In addition, NAP1L1 overexpression could upregulate HDGF expression in glioma cells, while NAP1L1 knockdown decreased the protein level expression of HDGF." (PMID 34959221, 2021). "Moreover, HDGF overexpression could upregulate c-Jun expression in glioma cells, while HDGF knockdown attenuated c-Jun expression at the protein level." (PMID 34959221, 2021). "Indeed, the interaction of HDGF and c-Jun in glioma cells was confirmed by endogenous co-IP assay." (PMID 34959221, 2021). "Interestingly, HDGF rescued SNHG3 silencing mediated promotion on apoptosis in glioma." (PMID 33817254, 2020).